NAA10 (N-alpha-acetyltransferase 10, NatA catalytic subunit)
Description:
Catalytic subunit of N-terminal acetyltransferase complexes which display alpha (N-terminal) acetyltransferase activity. Acetylates amino termini that are devoid of initiator methionine. The alpha (N-terminal) acetyltransferase activity may be important for vascular, hematopoietic and neuronal growth and development. Without NAA15, displays epsilon (internal) acetyltransferase activity towards HIF1A, thereby promoting its degradation. Represses MYLK kinase activity by acetylation, and thus represses tumor cell migration. Acetylates, and stabilizes TSC2, thereby repressing mTOR activity and suppressing cancer development. Acetylates HSPA1A and HSPA1B at 'Lys-77' which enhances its chaperone activity and leads to preferential binding to co-chaperone HOPX. Acetylates HIST1H4A. Acts as a negative regulator of sister chromatid cohesion during mitosis.
Synonyms: hARD1; ARD1; ARD1A; TE2; DXS707; ARD1P; LZMS; MAA; MCOPS1; NATD; OGDNS
Tractability: Small molecule: a structure with a bound ligand is known. PROTAC: ubiquitination databases record sites on it; its protein half-life has been measured.
Target class: Enzyme; Transferase
Gene: Protein-coding gene on chromosome X (153,929,225 to 153,935,080, reverse strand). Ensembl gene ENSG00000102030.
Subcellular location: Cytoplasm; Nucleus
Subcellular location (Human Protein Atlas): Cytosol; Nucleoli
Gene Ontology:
Molecular function: acetyltransferase activity; protein binding; protein N-terminal-serine acetyltransferase activity; protein-N-terminal amino-acid acetyltransferase activity; protein-N-terminal-alanine acetyltransferase activity; ribosome binding; N-acetyltransferase activity; protein-N-terminal-glutamate acetyltransferase activity; acyltransferase activity, transferring groups other than amino-acyl groups
Biological process: negative regulation of maintenance of mitotic sister chromatid cohesion, centromeric; positive regulation of protein refolding; protein maturation
Cellular component: cytoplasm; cytosol; membrane; NatA complex; nucleus
Gene-disease validity (ClinGen):
ClinGen rates the evidence that NAA10 causes each of these diseases.
NAA10-related syndrome (X-linked): Definitive. Ab X-linked syndromic intellectual disability in which the cause of the disease is a mutation in the NAA10 gene.
Homologues: Orthologues: chimpanzee NAA10 (100% identical), pig NAA10 (98% identical), rabbit NAA10 (97% identical), mouse Naa10 (96% identical), dog NAA10 (94% identical), macaque NAA10 (91% identical), tropical clawed frog naa10 (88% identical), guinea pig NAA10 (78% identical), zebrafish naa10 (78% identical), rat Naa10 (69% identical), Drosophila melanogaster vnc (57% identical), Caenorhabditis elegans daf-31 (53% identical). Paralogues in human: NAA11 (81% identical), NAA20 (23% identical), NAA30 (23% identical), NAA50 (18% identical).
Diseases named in the same sentence as NAA10 in open-access papers:
NAA10 is named in the same sentence as 89 diseases in open-access papers, as found by Europe PMC text mining. Sharing a sentence is not in itself a finding about the gene and the disease. The quoted sentences say what the papers report.
Ogden syndrome (23 papers, 2015 to 2025). Ogden syndrome is a rare, genetic progeroid syndrome characterized by a variable phenotype including postnatal growth delay, severe global developmental delay, hypotonia, non-specific dysmorphic facies with aged appearance and cryptorchidism, as well as cardiac arrthymias and skeletal anomalies. "Second, systemic toxicity is a potential risk due to NAA10′s essential roles in normal development, particularly in cardiac and neuronal functions, as evidenced by the severe phenotypes observed in Ogden syndrome patients with loss-of-function mutations." (PMID 40558489, 2025). "Mutations in the NAA10 gene have been linked to a spectrum of developmental disorders collectively referred to as NAA10-related syndromes, with Ogden syndrome (OMIM: 300855) being the most extensively studied." (PMID 40558489, 2025). "The NAA10 p.Ser37Pro variant, first identified in Ogden syndrome, introduces a proline residue that disrupts the coiled-coil structure and reduces binding affinity with NAA15." (PMID 40558489, 2025). "Pathogenic variants in NAA10 are linked to a spectrum of developmental disorders, most notably Ogden syndrome, which is characterized by neurodevelopmental delay, cardiac defects, and craniofacial anomalies." (PMID 40558489, 2025). "Ogden syndrome is a rare, X-linked developmental disorder caused by mutations in NAA10, which encodes the catalytic subunit of the NatA complex." (PMID 41148812, 2025). "As such, the interpretation of any results in this mouse model for the Ogden Syndrome Ser37Pro mutation are complicated by the knockdown of Naa10." (PMID 38713657, 2024). "After the advent of next-generation sequencing, more variants in the NAA10 gene and Ogden syndrome (OMIM# 300855) have been reported." (PMID 37441566, 2023). "Ogden syndrome is a rare lethal X‐linked recessive disorder caused by a recurrent missense variant (Ser37Pro) in the NAA10 gene, encoding the catalytic subunit of the N‐terminal acetyltransferase A complex (NatA)." (PMID 34075687, 2021). "Clinical features range from a severe phenotype in males, originally described as Ogden syndrome and associated with the missense variant p.Ser37Pro, to a milder NAA10-related intellectual disability (ID) caused by different variants in both males and females." (PMID 34200686, 2021). "The effect of the S37P mutation in the C-terminal end of helix α2 in the human Naa10 is causative of the lethal Ogden syndrome." (PMID 32206212, 2020). "The mutation causative of Ogden syndrome, S37P, leads to impaired NAA10 interaction with other NatA complex components, in addition to having decreased catalytic activity." (PMID 31174490, 2019). "Hemizygous variants were identified in two known X-linked disease genes: NAA10 (Ogden syndrome, ID and long QT, MIM 300855); and DDX3X previously associated with X-linked ID (MIM 300958)." (PMID 28327206, 2017). "We previously identified a disease, Ogden syndrome, associated with a S37P variant in the human Nα‐terminal acetyltransferase, Naa10." (PMID 27668839, 2017). "Deficiency of NAA10 is embryonic lethal, and a single mutation in NAA10 results in a perinatal lethality (known as Ogden syndrome), due to reduced activity of the NatA complex." (PMID 26646451, 2016). "NAA10 has previously been associated with Ogden syndrome, Lenz microphthalmia syndrome and non-syndromic developmental delay." (PMID 26522270, 2015). "The NAA10 variants causing non-syndromic developmental delay are de novo while the variants causing Ogden syndrome, LMS and syndromic development delay (current study) were inherited from carrier mothers." (PMID 26522270, 2015). "Ogden syndrome is an exceptionally rare X-linked disease caused by mutations in the NAA10 gene." (PMID 38335407, 2024). "NAA10 is involved in post-translational protein modifications, and mutations in NAA10 are known to cause Ogden syndrome, which may lead to growth failure." (PMID 36550527, 2022).
Ogden syndrome (continued). "Moreover, this set includes two N-termini of which the degree of NTA was previously found to be reduced in patient derived fibroblasts and/or B-cells harboring the Ogden syndrome mutation in the gene encoding NAA10 (i.e., NAA10 S37P)." (PMID 34639033, 2021). "In recent years, NAA10 variants have been found in patients with an X-linked developmental disorder called Ogden syndrome in its most severe form and, in other familial or de novo cases, with variable degrees of syndromic intellectual disability (ID) affecting both sexes." (PMID 29558889, 2018). "Our findings provide in vivo support for the pathogenicity of NAA10 dysfunction in cardiac tissue and highlight Drosophila as a powerful model system for studying Ogden syndrome." (PMID 41148812, 2025). "Molecular mechanisms of NAA10 in human diseases have been elucidated through detailed characterization of NAA10-related syndromes, particularly Ogden syndrome." (PMID 40558489, 2025). "In this study, we showed that Ogden syndrome can be modeled in Drosophila by silencing vnc, the Drosophila homolog of NAA10, specifically in the heart." (PMID 41148812, 2025). "Since 2011, eight males with an X-linked recessive disorder (Ogden syndrome, MIM #300855) associated with the same missense variant p.(Ser37Pro) in the NAA10 gene have been described." (PMID 34200686, 2021). "Given the clinical features in the family reported in this study, it is surprising that Naa10 Tyr43Ser results in a more severe impairment in catalytic activity compared to the Ogden syndrome mutant Naa10 Ser37Pro which is lethal." (PMID 26522270, 2015). "Although some do refer to this entire disease entity as Ogden syndrome, another name could be NAA10-related neurodevelopmental syndrome." (PMID 37130971, 2023). "Therefore, Ogden syndrome belongs to the broader group of genetic disorders, collectively described as NAA10-related syndrome." (PMID 36134023, 2022). "Over the years, many additional pathogenic NAA10 variants have been identified in NAA10 or NAA15 and the collection of presenting symptoms for families with NAA10 mutations is currently referred to as Ogden syndrome or NAA10-related syndrome." (PMID 34355692, 2021). "Thus, more detailed descriptions of the fatal NAA10‐related disorder are needed to fully understand the genetic and clinical heterogeneity of Ogden‐syndrome." (PMID 34075687, 2021). "NAA10-related syndrome is an X-linked condition with a broad spectrum of findings ranging from a severe phenotype in males with p.Ser37Pro in NAA10, originally described as Ogden syndrome, to the milder NAA10-related intellectual disability found with different variants in both males and females." (PMID 30054457, 2018). "After uncovering Ogden syndrome in 2011, reports of different nonlethal NAA10 variants in males as well as mostly de novo variants in affected female index cases with nonspecific ID have been published, expanding the clinical spectrum and elucidating the underlying complexity of NAA10 deficiency." (PMID 34075687, 2021). "The genetic landscape of variation in NAA10 and NAA15 in humans has been presented recently with many more cases of Ogden syndrome (OS) (also known as “NAA10-related neurodevelopmental syndrome”), and “NAA15-related neurodevelopmental syndrome”." (PMID 38713657, 2024). "This study demonstrated that the Ogden syndrome-causing NAA10 mutation disrupts the binding of NAA10 and DNMT1 to imprinting control regions of the genome, suggesting that the non-catalytic functions of NAA10 also contribute to the development and pathological phenotypes of NAA10-related syndromes." (PMID 40558489, 2025).
developmental delay (14 papers, 2015 to 2025). "The clinical features associated with pathogenic NAA10 mutations are variable, but commonly reported features include developmental delay, intellectual disability, cardiac anomalies, brain abnormalities, facial dysmorphism, and visual impairment." (PMID 40558489, 2025). "To gain insights, we studied a novel NAA10 variant (p.R4S) segregating with QT-prolongation, cardiomyopathy and developmental delay in a large kindred." (PMID 39070617, 2024). "Pathological variants in NAA10 cause NAA10-related syndrome, a rare multi-system disorder characterized by developmental delay, hypotonia, QT prolongation, arrhythmias, and increased mortality often before 1 year of age5." (PMID 39070617, 2024). "Individuals harboring NAA10 variants often display variable degrees of intellectual disability (ID), developmental delay, and cardiac anomalies." (PMID 32698785, 2020). "Although individuals harbouring NAA10 missense variants display phenotypic heterogeneity, the phenotypes observed in most affected individuals are developmental delay (DD), intellectual disability (ID) and cardiac anomalies." (PMID 33255974, 2020). "Recently, NAA10 germline variants were found in patients with the X-linked lethal Ogden syndrome, and in other familial or de novo cases with variable degrees of developmental delay, intellectual disability (ID) and cardiac anomalies." (PMID 31174490, 2019). "In both cases, males with severe developmental delay and microphthalmia in one individual, display hemizygous frameshift variants that leave the catalytic domain of NAA10 intact, hypothetically leading to a residual level of truncated protein lacking important regulatory regions." (PMID 34200686, 2021). "Here we report a novel NAA10 (NM_003491.3) c.248G > A, p.(R83H) missense variant in NAA10 which was detected by whole exome sequencing in two unrelated boys with intellectual disability, developmental delay, ADHD like behaviour, very limited speech and cardiac abnormalities." (PMID 31174490, 2019). "In addition, de novo missense mutations in the NAA10 gene have been identified in two independent cases of global developmental delay, and a truncated Naa10 protein is implicated in Lenz microphthalmia syndrome." (PMID 25914051, 2015). "Patients with NAA10-related syndromes invariably have intellectual disabilities and developmental delays, while cardiac arrhythmias, dysmorphic features, and hypotonia are also commonly seen, and there is considerable phenotypic variability." (PMID 34769235, 2021). "NAA10 p.(D10G) and NAA10 p.(L11R) were previously identified in a boy and a girl, respectively, with phenotypes including developmental delay and brain malformations." (PMID 33255974, 2020). "It is the first time to report variants in EFNB1, NAA10, DHCR7, LAMA1 and NFIX in Chinese intellectual disability/developmental delay patients and first report about variants in NAA10 and LAMA1 in affected individuals of Asian ancestry." (PMID 31088393, 2019). "Some Naa10-/Y mice had lower levels of somites and developmental delay." (PMID 34355692, 2021). "Hereditary or de novo germline variants in the X-chromosomal NAA10 gene is associated with developmental syndromes and non-syndromic developmental delay in humans." (PMID 31174490, 2019). "To date, all patients with NAA10 mutations show four common clinical features regardless of their syndrome; developmental delay (ranging from mild to severe), hypotonia, scoliosis and recurrent infections." (PMID 26522270, 2015). "While NAA10 mutations have a heterogenous clinical picture, with no clear genotype-catalytic activity-phenotype correlation, some features are seen in many or most patients; intellectual disability, developmental delay, growth failure, and cardiac anomalies." (PMID 31174490, 2019).
Intellectual disability (10 papers, 2015 to 2024). "A NAA10 p.(Tyr43Ser) variant was identified in two brothers with syndromic intellectual disability (ID) and long QT." (PMID 32698785, 2020). "Several mutations in human NAA10 are known, with substantial heterogeneity in presentation and severity of symptoms, yet with the common features of intellectual disability, delayed developmental and growth failure, and occasionally cardiac anomalies." (PMID 31174490, 2019). "However, recently it has been shown that NAA10 variants can cause syndromic or non-syndromic intellectual disability in females as well." (PMID 32698785, 2020). "Functional studies showed reduced acetylation activity of the mutant Naa10 enzyme implicating altered Nt-acetylation as one of the mechanisms contributing to the pathogenesis of syndromic intellectual disability." (PMID 26522270, 2015).
colon cancer (7 papers, 2016 to 2022). "The X-chromosomal NAA10 gene is essential for normal cell function, and dysregulation of NAA10 has been associated with several human cancers such as lung, breast, prostate and colon cancer." (PMID 33255974, 2020). "Our results implicate miR-342-5p and miR-608 in colon cancer development and unveil the underlying mechanism of this phenomenon, which involves NAA10." (PMID 26646451, 2016). "Previous studies have shown that NAA10 is upregulated in colorectal cancer and is associated with poor prognosis in colon cancer patients, however, the role of NAA10 in colon cancer development remains largely unknown." (PMID 26646451, 2016). "It inhibits colon cancer tumorigenesis through direct targeting of the N-a-acetyl transferase 10 protein (NAA10) and also promotes apoptosis." (PMID 34070455, 2021). "Given the complexity of NAA10 regulation of cancer development, further studies are needed to uncover the molecular mechanisms behind how NAA10 controls colon cancer tumorigenesis." (PMID 26646451, 2016). "Collectively, these results indicate that NAA10 can partially rescue colon cancer tumorigenesis that is repressed by miR-342-5p or miR-608 overexpression in vitro." (PMID 26646451, 2016). "In this work, we demonstrated that miR-342-5p and miR-608 directly targeted NAA10 mRNA and reduced the expression of NAA10, therefore inhibiting colon cancer tumorigenesis." (PMID 26646451, 2016). "Here we showed that miR-342-5p and miR-608 suppressed the tumorigenesis of colon cancer cells in vitro and in vivo by targeting NAA10 mRNA for degradation." (PMID 26646451, 2016). "Accordingly, we observed reduced expression of miR-342-5p and miR-608 in patient-derived colon cancer samples, which was inversely correlated with the expression of NAA10." (PMID 26646451, 2016). "Our results have extended the tumor suppressive function of miR-608 to include colon cancer and have validated NAA10 as a new target of miR-608." (PMID 26646451, 2016). "Our results suggested that silencing NAA10 led to lower level of colon cancer cell tumorigenesis in vitro." (PMID 26646451, 2016). "In this study, we attempted to identify miRNAs regulating NAA10 expression and further demonstrated their roles in colon cancer tumorigenesis." (PMID 26646451, 2016). "Moreover, Yang and colleagues reported that miR-608 suppressed the carcinogenesis of colon cancer cells in vitro and in vivo by eliminating NAA10 mRNA which participate as a key molecule in the process of carcinogenesis." (PMID 27223084, 2017). "Our results suggest that NAA10 may serve as a potential target for colon cancer therapy, and miR-342-5p and miR-608 may have potential therapeutic applications in colon cancer patients." (PMID 26646451, 2016). "Combined with the fact that NAA10 was upregulated in tumors, these data indicated NAA10 might act as an oncogene in colon cancer." (PMID 26646451, 2016). "Thus, miRNA-342-5p and miR-608 suppress colon cancer tumorigenesis most likely by downregulating NAA10." (PMID 26646451, 2016).
microphthalmia (6 papers, 2020 to 2022). Congenital or developmental anomaly in which the eyeballs are abnormally small. "Polyadenylation signal variants, resulting in a decreased quantity of NAA10 RNA, seemed to be related to a distinct clinical phenotype in males, NAA10-associated syndromic microphthalmia." (PMID 34200686, 2021). "Compared to missense variants, alterations in the NAA10 gene which result in a (partial) loss of protein function due to reduced mRNA levels can lead to syndromic microphthalmia/anophthalmia in boys." (PMID 34075687, 2021). "Patients with NAA10 mutations in further unstructured domains (exons 7 or 8) tend to exhibit microphthalmia or anophthalmia." (PMID 32864149, 2020). "Furthermore, a frameshift variant, a splice-site variant and three PAS variants in NAA10 have been associated with syndromic microphthalmia in 20 males." (PMID 35039925, 2022). "However, only polyadenylation signal (PAS) variants, splice and frameshift variants in NAA10 have been found to cause microphthalmia." (PMID 35039925, 2022). "Further investigations are needed to clarify the precise mechanism of microphthalmia in NAA10-related syndrome." (PMID 32864149, 2020).